LCK (LCK proto-oncogene, Src family tyrosine kinase)
Description:
Non-receptor tyrosine-protein kinase that plays an essential role in the selection and maturation of developing T-cells in the thymus and in the function of mature T-cells. Plays a key role in T-cell antigen receptor (TCR)-linked signal transduction pathways. Constitutively associated with the cytoplasmic portions of the CD4 and CD8 surface receptors. Association of the TCR with a peptide antigen-bound MHC complex facilitates the interaction of CD4 and CD8 with MHC class II and class I molecules, respectively, thereby recruiting the associated LCK protein to the vicinity of the TCR-CD3 complex. LCK then phosphorylates tyrosine residues within the immunoreceptor tyrosine-based activation motifs (ITAM) of the cytoplasmic tails of the TCR-gamma chains and CD3 subunits, initiating the TCR-CD3 signaling pathway. Once stimulated, the TCR recruits the tyrosine kinase ZAP70, that becomes phosphorylated and activated by LCK. Following this, a large number of signaling molecules are recruited, ultimately leading to lymphokine production. LCK also contributes to signaling by other receptor molecules. Associates directly with the cytoplasmic tail of CD2, which leads to hyperphosphorylation and activation of LCK. Also plays a role in the IL2 receptor-linked signaling pathway that controls the T-cell proliferative response. Binding of IL2 to its receptor results in increased activity of LCK. Is expressed at all stages of thymocyte development and is required for the regulation of maturation events that are governed by both pre-TCR and mature alpha beta TCR. Phosphorylates other substrates including RUNX3, PTK2B/PYK2, the microtubule-associated protein MAPT, RHOH or TYROBP. Interacts with FYB2.
Synonyms: LSK; IMD22; YT16; p56lck; pp58lck
Tractability: Small molecule: an approved drug acts on it; a structure with a bound ligand is known; a high-quality ligand is known; it has a high-quality binding pocket; it belongs to a druggable protein family. Antibody: UniProt places it where antibodies can reach, with high confidence; its Gene Ontology location is reachable by antibodies, with high confidence. PROTAC: it is named in the literature on targeted protein degradation; UniProt records ubiquitination sites on it; ubiquitination databases record sites on it; its protein half-life has been measured; a small molecule that binds it is known.
Target class: Kinase; TK protein kinase group; Enzyme; Protein Kinase; Tyrosine protein kinase Src family
Chemical probes: A-770041 (high quality), DGY-06-116 (high quality), PD080821, PD081045, PD081470, PD082075, PD082119, PD082239, PD082700, PD083050, PD083127, PD083706, PD085050, PD085056, WH-4-023
Safety:
Unwanted effects reported when the protein is acted on. In parentheses: how it was acted on, where the effect was seen, and who reports it.
SCID-like immunodeficiency (inhibition; Immune; source: Bowes et al. (2012))
T cell activation (activation; Immune; source: Bowes et al. (2012))
T cell inhibition (inhibition; Immune; source: Bowes et al. (2012))
Gene: Protein-coding gene on chromosome 1 (32,251,244 to 32,286,170, forward strand). Ensembl gene ENSG00000182866.
Subcellular location: Cell membrane; Cytoplasm, cytosol
Subcellular location (Human Protein Atlas): Golgi apparatus
Pathways (Reactome):
Immune System: CD28 dependent PI3K/Akt signaling; CD28 dependent Vav1 pathway; Co-inhibition by CTLA4; Co-inhibition by PD-1; Co-stimulation by CD28; DAP12 signaling; Downstream TCR signaling; FLT3 signaling through SRC family kinases; Generation of second messenger molecules; Interleukin-2 signaling; Phosphorylation of CD3 and TCR zeta chains; Translocation of ZAP-70 to Immunological synapse
Signal Transduction: PI5P, PP2A and IER3 Regulate PI3K/AKT Signaling; PIP3 activates AKT signaling; RHOH GTPase cycle; Regulation of KIT signaling; Signaling by SCF-KIT
Disease: Constitutive Signaling by Aberrant PI3K in Cancer; Nef Mediated CD4 Down-regulation; Nef and signal transduction; Signaling by phosphorylated juxtamembrane, extracellular and kinase domain KIT mutants
Hemostasis: GPVI-mediated activation cascade; PECAM1 interactions
Gene Ontology:
Molecular function: ATPase binding; CD4 receptor binding; CD8 receptor binding; identical protein binding; non-membrane spanning protein tyrosine kinase activity; phosphatidylinositol 3-kinase binding; phospholipase activator activity; phospholipase binding; phosphotyrosine residue binding; protein binding; protein kinase binding; protein phosphatase binding; protein serine/threonine phosphatase activity; protein tyrosine kinase activity; SH2 domain binding; T cell receptor binding; signaling receptor binding; ATP binding; protein antigen binding; protein kinase activity
Biological process: CD27 signaling pathway; Fc-gamma receptor signaling pathway; intracellular signal transduction; NK T cell activation; positive regulation of heterotypic cell-cell adhesion; positive regulation of intrinsic apoptotic signaling pathway; positive regulation of leukocyte cell-cell adhesion; positive regulation of T cell activation; response to xenobiotic stimulus; T cell activation; T cell differentiation; T cell receptor signaling pathway; B cell receptor signaling pathway; cell surface receptor protein tyrosine kinase signaling pathway; hemopoiesis; leukocyte migration; platelet activation; positive regulation of T cell receptor signaling pathway; regulation of lymphocyte activation; release of sequestered calcium ion into cytosol; T cell costimulation; immune response-activating cell surface receptor signaling pathway; positive regulation of multicellular organismal process
Cellular component: cytoplasm; extracellular exosome; immunological synapse; membrane raft; pericentriolar material; plasma membrane; cytosol; cell-cell junction
Genetic constraint (gnomAD): Loss-of-function variants: 14 observed, 65.94 expected, observed/expected ratio (o/e) 0.21, 90% interval 0.14 to 0.33. The upper end of that interval is the gene's LOEUF score, 0.33, which puts it in group 1 of 6, group 1 being the genes least tolerant of losing a copy. Missense variants: 434 observed, 687.88 expected, observed/expected ratio (o/e) 0.63, 90% interval 0.58 to 0.68. Synonymous variants: 277 observed, 268.96 expected, observed/expected ratio (o/e) 1.03, 90% interval 0.93 to 1.14.
Gene-disease validity (ClinGen):
ClinGen rates the evidence that LCK causes each of these diseases.
severe combined immunodeficiency due to LCK deficiency (autosomal recessive): Definitive.
Cancer hallmarks: proliferative signalling (promotes); escaping programmed cell death (suppresses); angiogenesis (suppresses); escaping programmed cell death (promotes)
Homologues: Orthologues: chimpanzee LCK (99% identical), macaque LCK (99% identical), dog LCK (97% identical), rabbit LCK (97% identical), mouse Lck (97% identical), rat Lck (96% identical), pig LCK (96% identical), guinea pig LCK (96% identical). Paralogues in human: HCK (65% identical), LYN (63% identical), BLK (60% identical), FYN (57% identical), YES1 (56% identical), SRC (54% identical), FGR (53% identical), FRK (46% identical), ABL2 (42% identical), ABL1 (41% identical), SRMS (39% identical), PTK6 (36% identical), and 20 more.
Diseases named in the same sentence as LCK in open-access papers:
LCK is named in the same sentence as 180 diseases in open-access papers, as found by Europe PMC text mining. Sharing a sentence is not in itself a finding about the gene and the disease. The quoted sentences say what the papers report.
breast cancer (26 papers, 2007 to 2025). A primary or metastatic malignant neoplasm involving the breast. "LCK has been implicated in leukemia, breast cancer, lung cancer, bile duct cancer, gliomas, colorectal cancer, and melanomas." (PMID 40565031, 2025). "In the PPI network of 308 genes, several hub genes (ESR1, BRCA1, CREBBP, ERBB2, and LCK) are known to play critical roles in breast cancer development." (PMID 39888956, 2025). "In BL1, the enriched kinases, such as LCK and PTK2B, were associated with tumorigenesis, as well as invasion of breast cancer, whereas ZAP70 was reported to be related to drug resistance in TNBC." (PMID 36672350, 2023). "Currently, LCK has been shown to function as an oncogene in leukaemia and various solid cancers, including breast cancer, colon cancer, and lung carcinoma." (PMID 35665750, 2022). "In breast cancer, LCK promotes angiogenesis and tumor progression, indicating an oncogenic role in line with our findings." (PMID 34830895, 2021). "In breast cancer, LCK was shown to enhance or suppress cell motility and invasiveness in a context-dependent manner." (PMID 34116687, 2021). "Lck (LCK) plays a pathological role in breast cancer progression probably by activating MAPK signaling pathway." (PMID 33246450, 2020). "To identify immune-related prognostic markers and therapeutic targets, we determined the lymphocyte-specific kinase (LCK) metagene scores of samples from breast cancer patients in The Cancer Genome Atlas." (PMID 31715586, 2019). "The result presented here reinforces the functional implication of LCK in the context of HER2-enriched breast cancer and emphasizes the necessity of further, focused studies." (PMID 27920729, 2016). "Based on breast cancer networks' centrality, we identify genes previously associated to the disease, either, generally (i.e., CNR2) or to a particular subtype (such as LCK)." (PMID 27920729, 2016). "FOXP3 is reported to be a mammary tumor suppressor and LCK is expressed in breast cancer tissues and cell lines." (PMID 24155921, 2013). "LCK is highly expressed in most cancers, including breast cancer, colorectal cancer and glioma." (PMID 36341345, 2022). "Based on the current evidence, BRCA1 and LCK metagene expression may be independent markers of breast cancer." (PMID 31715586, 2019). "However, high expression of LCK in estrogen-receptor positive and negative breast cancer samples was associated with a better metastasis-free survival." (PMID 34116687, 2021). "In this study, the core components regulate five key targets: MAPK1, LCK, JAK2, HSP90AA1, and EGFR, all of which are uniquely expressed in breast cancer." (PMID 39867914, 2024). "This included cetuximab (as in the breast cancer specific analysis), IGF1R and LCK inhibitors, all identified to modulate the SAC." (PMID 37707389, 2023). "Paradoxically, in human breast cancer, LCK suppresses cellular invasion by decreasing MMP9, SKP2, and VEGF-A expression but promotes the metastasis of breast cancer." (PMID 36430477, 2022). "Our results suggest that the PR status has a profound effect on tyrosine kinases, especially for FGFR4 and LCK genes, in ER+/HER2− breast cancer patients." (PMID 32710281, 2020). "In TCGA data provided by the Cancer Genome Atlas, we find HCK, LYN, LCK, and CSK are higher in basal-like breast cancer subtypes." (PMID 28771473, 2017). "Both LCK and LYN regulate migration and inhibition and LYN reduces breast cancer metastasis." (PMID 35150959, 2022). "In order to illustrate how the same genes may have different roles in different breast cancer manifestations, we selected, based on their degree in each breast cancer network, the CNR2, LCK, and LUZP4 genes." (PMID 27920729, 2016). "Lymphocyte-specific protein tyrosine kinase (LCK), a member of the Src family of non-receptor protein tyrosine kinases, is mostly expressed in T cells, normal breast tissue, and breast cancer tissue and cell lines." (PMID 24155921, 2013).
breast cancer (continued). "Notably, LCK showed significantly higher expression in TNBC compared to normal tissues and other breast cancer subtypes, whereas MAPK1 and JAK2 exhibited much lower expression in TNBC compared to normal tissues and other breast cancer subtypes." (PMID 39867914, 2024).
glioma (22 papers, 2019 to 2025). A benign or malignant brain and spinal cord tumor that arises from glial cells (astrocytes, oligodendrocytes, ependymal cells). "Fyn, Yes1, and Src were consistently expressed in both glioma stem cells and primary glioma cells among SFKs, whereas LCK was exclusively expressed in primary glioma cells." (PMID 38338729, 2024). "LCK is an oncogene which has been reported to promote oral cancer metastasis, glioma growth and ovarian tumor cisplatin resistance." (PMID 38321024, 2024). "Previous studies reported that LCK is an oncogene and the use of LCK inhibitors can inhibit glioma growth, metastasis and the expression of cell stemness-related genes, and enhance cisplatin sensitivity in ovarian cancer." (PMID 38321024, 2024). "This is also corroborated by previous findings that indicate fractionated radiation induces stem cell populations in human gliomas to display LCK activation." (PMID 37370140, 2023). "On the contrary, proteins related to T cell activation, such as LCK, presented a positive correlation with the signature, implying the dysfunction of T cells happened in glioma." (PMID 33531060, 2021). "Intriguingly, inhibition of LCK reduced the formation of pseudopodia and the migration of glioma cells in a human glioma cell-axon-oligodendrocyte co-culture model." (PMID 34116687, 2021). "TOX expression was negatively associated with inflammatory activity signatures including HCK, LCK, MHC-I, MHC-II, STAT1, and interferon metagenes, but positively associated with the IgG metagene in pan-glioma analysis, LGG alone, and GBM alone." (PMID 32762688, 2020). "LCK inhibitors could be used to regulate glioma cell movement, cancer invasion, and stem cell gene expression." (PMID 35480305, 2022). "Furthermore, based on seven clusters of metagenes, GSVA identified that ICOS was tightly associated with HCK, LCK, MHC-I, MHC-II, STAT1, and interferon, especially with LCK, suggesting a strong correlation between ICOS and T-cell activity in gliomas." (PMID 36276141, 2022). "Consequently, TNFSF13 expression was identified positively correlated with interferon, STAT1, MHC-I, MHC-II, HCK, and LCK, while negatively relevant to IgG metagene in pan-glioma analysis and GBM alone analysis in both TCGA and CGGA databases." (PMID 34712225, 2021). "Furthermore, LCK participates in many malignant biological processes in glioma, such as migration, tumor growth, and regulation of cancer stemness." (PMID 31672930, 2019). "The results showed that IgG, HCK, MHC-II, LCK, STAT1 interferon, B7-CD28, and TNF-related tumor immune responses were significantly enhanced with the increasing risk scores, indicating that the immune microenvironment in high-risk glioma patients regulates response changes." (PMID 37228500, 2023). "In both the TCGA and CGGA datasets, TREM1 expression was found to be positively correlated with HCK, interferon, LCK, MHC-I, MHC-II, and STAT1 metagenes but negatively correlated with IgG metagenes in glioma." (PMID 38370418, 2024). "PDIA3 expression was positively correlated with HCK, LCK, MHC-I, MHC-II, STAT1, and interferon, but negatively related to IgG in pan-glioma and GBM analysis based on both TCGA and CGGA datasets." (PMID 32687065, 2020). "Still only BMP2, MMP13, MMP2, LCK, MMP9, and AR have been reported to affect the glioma invasion." (PMID 39458959, 2024). "We then further investigated the effects of ALKBH5 expression on the tumor immune microenvironment (TIM) of glioma by screening seven metagenes, namely, HCK, IgG, Interferon, LCK, MHC-I, MHC-II, and STAT1, which reflect the status of inflammation and immune responses." (PMID 35444654, 2022). "The relationship between B2M and seven inflammatory activity related signatures was then explored in pan-gliomas and LGG, B2M expression had positive correlation with HCK, LCK, MHC-I, MHC-II, STAT1 and interferon metagenes, and negative correlation with IgG metagene expression." (PMID 33658560, 2021).
glioma (continued). "We discovered that LIGHT expression exhibited a positive correlation with HCK, interferon, LCK, MHC-I, MHC-II, and STAT1 metagenes in all gliomas, while IgG exhibited a negative correlation with LIGHT expression based on the TCGA and CGGA datasets." (PMID 36341396, 2022). "LCK appears to be expressed in primary glioma cells but not in the paired glioma stem cells from the same human GBM tumors, which indicates that LCK activity is not necessary for the maintenance of glioma stem cells." (PMID 32237064, 2020).
leukemia (16 papers, 2011 to 2025). A malignant (clonal) hematologic disorder, involving hematopoietic stem cells and characterized by the presence of primitive or atypical myeloid or lymphoid cells in the bone marrow and the blood. "Mutated and overexpressed LCK drive leukemia cell proliferation." (PMID 33999861, 2021). "In addition, mutated and overexpressed LCK is driving leukemia cell proliferation." (PMID 33999861, 2021). "A recent study showed that dasatinib, an LCK inhibitor, enhanced the anti-leukemia efficacy of CAR-T cells by inhibiting cell differentiation and exhaustion." (PMID 36430477, 2022). "Together, these findings demonstrate that USP11 and USP7 form an oncogenic complex with LCK in leukemia." (PMID 36490346, 2022). "Impairment of LCK activity impedes T cell signaling, leading to up-regulation of GC receptor (GR) expression, which sensitizes the leukemia cells to GCs." (PMID 36490346, 2022). "We demonstrate that LCK is substantially overexpressed and constitutively activated in leukaemia cells from patients with indolent CLL while its expression level and activation status in aggressive CLL was comparable to physiological B cells." (PMID 28970470, 2017). "The over-expression schizophrenia genes involving the SYK and LCK genes play a key role in functional modularity in T cell, leukemia and lymphocyte activation which is crucial in immune-related responses." (PMID 24564241, 2013). "The lymphocyte-specific protein tyrosine kinase (LCK) is a critical target in leukemia treatment." (PMID 37959801, 2023). "Indeed, several LCK inhibitors have been approved to treat leukemia and various solid cancers, including pancreatic cancer." (PMID 35665750, 2022). "However, CYLD expression is repressed in T-ALL patient samples, and our data demonstrate that LCK is differentially regulated in the thymus compared to leukemia settings." (PMID 36490346, 2022). "LCK has recently been reported as a key molecule in multiple subsets of leukemia." (PMID 25595912, 2015). "In agreement with this hypothesis, several of the genes identified in our analysis have been suggested to be putative therapeutic targets in leukemia, with either preclinical or clinical trials underway (CDK4, CDK6, GSK3b, MYC, LCK, NFkB2, BCL2L1, NOTCH1)." (PMID 21356087, 2011). "In the present study we demonstrated that both these aberrancies are not only necessary to drive leukemia, but they are a direct consequence of the expression of the PAX5 fusion protein, which can a) repress the activity of endogenous PAX5 and b) activate STAT5 through LCK." (PMID 25595912, 2015). "CAR T cells overexpressing LCK and ZAP70 showed effects in improving anti-leukemia function, but they were not as good as C-JUN overexpression." (PMID 39039086, 2024).